MUC1 (mucin 1, cell surface associated)
Diseases named in the same sentence as MUC1 in open-access papers (continued):
Sharing a sentence is not in itself a finding about the gene and the disease.
Autoimmunity (4 papers, 2014 to 2021). The occurrence of an immune reaction against the organism's own cells or tissues. "In this article, we will discuss the experimental evidence supporting MUC1 as a putative regulatory molecule or a “checkpoint molecule” of T cells with implications as a novel biomarker and therapeutic target in chronic diseases such as autoimmunity, inflammation and cancer, and possibly infections." (PMID 30405607, 2018). "Subsequent studies from different laboratories, as well as ours, supported an immuno-regulatory role of MUC1 in infections, inflammation, and autoimmunity that corroborated our original findings establishing MUC1 as a novel T cell regulatory molecule." (PMID 30405607, 2018). "For example, vaccines against self/tumor antigens MUC1 and α-lactalbumin have shown clinical and preclinical efficacy with no induction of autoimmunity." (PMID 24596571, 2014).
biliary tract cancer (4 papers, 2021 to 2025). "A phase I study of the MUC1 vaccine in advanced pancreatic and biliary tract cancers, which included three patients with biliary tract cancer, concluded that the vaccine was safe." (PMID 34440865, 2021).
carcinoma in situ (4 papers, 2008 to 2018). "In case of carcinoma in situ, intense MUC1 staining (mean intensity 2.9±0.1 and mean H-score 2.48±0.74) was observed (N = 10) in the tissue sections." (PMID 24671186, 2014). "The observation that MUC1 overexpression begins in metaplastic and dysplastic lesions and in carcinoma in situ suggests that a MUC1 peptide-based vaccination may be useful as a chemoprevention strategy." (PMID 30479696, 2018). "There was an inverse correlation between positivity for serum anti-MUC1 AAbs and extent of disease; while 3/6 (50%) patients with a carcinoma in situ were positive, only 1/15 (6.7%) patients with more than five nodes involved had elevated levels of anti-MUC1 AAbs." (PMID 21113302, 2010). "MUC1 expression in non-invasive papillary urothelial carcinoma and urothelial Carcinoma In Situ (CIS)." (PMID 24671186, 2014).
cervical tumors (4 papers, 2005 to 2024). "To explore the role of MUC1 in the early diagnosis of cervical squamous cell carcinoma, we analyzed MUC1 expression in different types of cervical neoplasms." (PMID 38702644, 2024). "Mucin 1 (MUC-1), which is a transmembrane glycoprotein overexpressed in cervix tumor cells, has been found to be involved in PTX chemoresistance in an EGFR-dependent manner." (PMID 33348838, 2020). "In contrast, only MUC1 levels increased with no significant changes in expression of MUC5B and MUC8 in cervical tumors over normal cervical tissues." (PMID 16188033, 2005).
clear cell adenocarcinoma (4 papers, 2019 to 2025). A malignant neoplasm composed of glandular epithelial clear cells. "Therefore, it is important to assess whether clinical features and biological characteristics of clear cell adenocarcinoma are influenced by the presence of MUC1." (PMID 34641504, 2021). "Five most downregulated genes in clear cell carcinoma include, ITGB6 (−9.09-fold), MUC1 (−5.00-fold), CDH1 (−3.57-fold), HIF1A (−2.27-fold) and FOS (−1.96-fold)." (PMID 30863721, 2019).
endometrial adenocarcinoma (4 papers, 2005 to 2021). "The endometrial adenocarcinoma HEC-1 cell line was selected for this study as the cell line expresses MUC1 (HEC-1B is a substrain of HEC-1A) and has been widely used in implantation research." (PMID 33596915, 2021). "In addition to Muc1, they were also positive for E-cadherin and anti-fibroblast staining, which is characteristic for endometrial adenocarcinoma cells that demonstrate epithelial-to-mesenchymal transition." (PMID 31417529, 2019). "While upregulation of progesterone increased cytoplasmic expression of MUC1 in normal cycling endometrium, negative MUC1 was significantly related to PR expression and marginally correlated with loss of ER in endometrial adenocarcinoma (EMA)." (PMID 16409624, 2006). "One significant conclusion that can be drawn from this study is that mucin genes, MUC1, MUC5B and MUC8 are all up-regulated in endometrial adenocarcinomas." (PMID 16188033, 2005). "Statistically, higher levels of MUC1, MUC5B and MUC8 were observed in endometrial adenocarcinomas compared to normal tissues." (PMID 16188033, 2005).
endometrial tumor (4 papers, 2005 to 2024). "Overall, these results demonstrate that MUC1KrasPten mice represent the first immune competent, orthotopic, human MUC1-expressing preclinical tumor model for epithelial cell- derived oviduct and endometrial tumors." (PMID 25078979, 2014). "Finally, MUC1 and EGFR co-expression was associated with increased cellular proliferation in human endometrial tumors." (PMID 27092881, 2016). "Overall, the percent of endometrial tumor tissue with observed MUC1 expression was 29.5% (± 3.7% SEM), EGFR expression was 40.2% (± 3.9% SEM) and MUC1/EGFR co-expression was 14.3% (± 2.2% SEM)." (PMID 27092881, 2016). "Endometrial tumors showed increased expression of MUC1, MUC5B and MUC8 over normal tissues." (PMID 16188033, 2005).
intestinal infection (4 papers, 2008 to 2021). "While MUC5AC is considered protective, alterations in the MUC1 expression in both directions have been associated with intestinal infections and inflammation." (PMID 34685068, 2021). "The importance of the constitutive expression of mucins has been highlighted by mouse models deficient of MUC1, MUC2, and MUC13, revealing elevated susceptibilities towards intestinal infections, inflammations and spontaneous tumors." (PMID 34685068, 2021). "In conclusion, in response to intestinal infection mucin secretion is increased and most mucins are depleted from the epithelium whilst MUC1 is upregulated." (PMID 19088856, 2008). "Yet, further research is required to clarify whether the alterations of MUC1, MUC2 and MUC13 expression are physiologically relevant for the susceptibility towards intestinal infections and inflammations." (PMID 34685068, 2021). "The effects on MUC1 and MUC2 suggest that specific ENM may lead to an elevated susceptibility towards intestinal infections and inflammations." (PMID 34685068, 2021). "Our data provide evidence that glycosylated MUC1 serves as a receptor for intestinal infection in several non-typhoid Salmonella enterica serovars." (PMID 30716138, 2019). "However, the role of MUC1 during intestinal infections has not been previously explored, and our results describe the first report of MUC1 as a proinflammatory factor following intestinal infection." (PMID 28588132, 2017). "Cell-surface mucins are likely to play an important role in mucosal defense since they may provide both a barrier and reporting function, and we have demonstrated increased pathology following gastrointestinal infection in mice lacking the Muc1 cell surface mucin." (PMID 19088856, 2008).
laryngeal carcinoma (4 papers, 2014 to 2025). Carcinoma that arises from the laryngeal epithelium. "We anticipate that by targeting mucin‐overexpressing laryngeal cancer cells, the chitosan‐coated liposomes will electrostatically bind to transmembrane mucins like MUC1, MUC4, MUC17 and thus enhance the drug intake and retention process." (PMID 40385549, 2025). "The mucin‐related genes, MUC1 and MUC4, are overexpressed in treatment‐resistant laryngeal carcinoma." (PMID 40385549, 2025). "Mucin 1 (MUC1) is a transmembrane glycoprotein which is expressed in normal epithelial cells, but it was overexpressed and aberrantly glycosylated in majority of carcinomas, including laryngeal cancer." (PMID 32662743, 2020).
malignant mesothelioma (4 papers, 2006 to 2020). A malignant neoplasm of the pleura or peritoneum, arising from mesothelial cells. "Moreover, compared with benign mesothelial cells, MUC1 was significantly higher in malignant mesothelioma." (PMID 31666098, 2019). "In cases of malignant mesothelioma there is an increase in the total quantity of MUC1-TM mRNA expressed, a change in the type of MUC1 isoform produced, an alteration in the epitopes of MUC1 expressed on cell surface and an increase in MUC1 gene product detectable in the circulation." (PMID 18454162, 2008).
metastasis (4 papers, 2016 to 2025). The spread or migration of cancer cells from one part of the body (where they first appeared) to another. "Specifically, MUC‐1 were obtained from a distant ACC neck metastasis, while TVBF‐7 were established from a perirenal lymph‐node metastasis." (PMID 39528354, 2025).
Mucinous tumors (4 papers, 2011 to 2025). "In our ovarian cases, one mucinous tumor, MUC1, harbours a fusion between ERBB2 and adjacent PERLD1 caused by an underlying genomic inversion." (PMID 21625565, 2011). "We found positive correlations between mucinous differentiation and the expression of all five mucins, except for the membranous MUC1 expression, indicating higher mucin levels in mucinous versus non-mucinous tumours." (PMID 39966658, 2025). "Furthermore, it was found out that MUC1, MUC1-core, and TF are especially expressed in mucinous tumors (as well in primary tumors as in the corresponding metastases), while CA19-9, CA50, and CA242 seemed to be more characteristic for gastrointestinal tumors." (PMID 26528431, 2015).
Obesity (4 papers, 2023 to 2025). Accumulation of substantial excess body fat. "The data in this study indicate that upregulation of MUC1 is associated with an increased risk of obesity." (PMID 38716942, 2024). "MUC1 can also provide information on the direction of the relationship between obesity and cancer." (PMID 38716942, 2024). "In conclusion, MUC1 appears to be capable of modulation on its own, without being overshadowed by HbA1c and NF-κB in obesity." (PMID 38716942, 2024). "There are no studies on the reflections of the relationship between MUC1 and the other two genes (HbA1c and NF-κB) in obesity physiology." (PMID 38716942, 2024). "Furthermore, the expression of MUC-1 and E-cadherin remained unchanged across all groups, indicating that these markers were not affected by either PCOS status or obesity." (PMID 41195204, 2025).
ovarian adenocarcinoma (4 papers, 2016 to 2023). An adenocarcinoma that arises from the ovary. "Given the promising preclinical characterisation of [177Lu]Lu-DOTA-C595 in PDAC, future research should consider applying [177Lu]Lu-DOTA-C595 to other epithelial malignancies with MUC1-CE overexpression such as lung, colon and ovarian adenocarcinoma." (PMID 37578571, 2023).
prostate tumors (4 papers, 2004 to 2025). "Using PAC120, a xenograft of a human hormone-dependent prostate tumour, and its hormone-independent variants, we analysed the expression of mucins (MUC1, MUC2, MUC4, MUC5AC, MUC5B, MUC6) by immunohistochemistry or reverse transcriptase (RT)–PCR." (PMID 14760390, 2004). "In particular, we found primarily overexpression of CTNNB1, CDH1, SMAD2, SMAD3, TCF3, LEF1 in younger patients and overexpression of SNAI1 and underexpression of KRT5, KRT19, OCLN, CDH2 and MUC1 which clearly indicates different characteristics of prostate tumor in younger vs older patients." (PMID 29206234, 2017). "Anti-MUC1 di-scFvs has been developed as an effective agent for targeted radioimmunotherapy (RIT) to increase the therapeutic index of RIT in epithelial cancers such as prostate tumors." (PMID 24391668, 2013).
proteinopathies (4 papers, 2022 to 2024). "This MUC1-fs mutation provokes a proteinopathy in which the MUC1-fs protein accumulates in the early secretory pathway of epithelial cells where it is thought to exert its harmful effect via dysregulation of the unfolded protein response pathway." (PMID 37316299, 2023). "Mucin 1 kidney disease (MKD) is a toxic proteinopathy caused by MUC1 frameshift (MUC1-fs) mutation." (PMID 35309912, 2022). "The proteinopathy mucin-1 kidney disease (MKD) results from a frameshift mutation in the MUC1 gene." (PMID 36733337, 2022).
renal failure (4 papers, 2020 to 2024). "Among the nineteen affected individuals with MUC1 mutations, twelve (7 females and 5 males) had abnormal renal function, and the age at onset of renal insufficiency ranged from 29 to 75 years (median: 46 years)." (PMID 32451462, 2020). "We speculated that IV-56 was an affected individual since he had elevated SCr, his father had renal insufficiency and his brother had an MUC1 mutation that was confirmed by genetic testing." (PMID 32451462, 2020).
T-cell leukemia (4 papers, 2017 to 2020). A malignant disease of the T-lymphocytes in the bone marrow, thymus, and/or blood. "In addition, targeting the cancer-associated Tn glycoform of MUC1 using genetically modified T cells expressing a chimeric receptor (CAR T cells) has shown efficacy in xenograft models of T cell leukemia and pancreatic cancer." (PMID 30135430, 2018). "It was observed that anti-Tn-MUC1 CAR-T-cells mediated target-specific cytotoxicity and successfully controlled tumor growth in xenograft models of T-cell leukemia, suggesting the therapeutic efficacy of CAR-T-cells directed against Tn-MUC1." (PMID 28116322, 2017).
tubulointerstitial kidney disease (4 papers, 2021 to 2026). "Of note, multiple single cytosine insertions in the coding VNTR region of MUC1, another mucin family member, were identified as the main cause of medullary cystic kidney disease type 1, an autosomal dominant tubulointerstitial kidney disease." (PMID 41541775, 2026). "Tubulointerstitial kidney disease (TIKD): The well-established MUC1 cytosine duplication variant was detected in 6 families (25 patients) with ADTKD." (PMID 35099770, 2022).
uterine tumor (4 papers, 2014 to 2025). "KrasPten-driven uterine tumors express human MUC1 and trigger spontaneous anti-MUC1 antibodies." (PMID 39975595, 2025). "In this study, we examined whether the oviductal and uterine tumors also expressed MUC1 upon Kras activation and Pten deletion in MUC1KrasPten mice." (PMID 25078979, 2014). "We investigated the expression of 11 genes selected for their importance as potential biomarkers of epithelial cells (CK19, MUC1, HER family), cervical uterine tumor cells (HPV16-E6), or for their involvement in tumor progression (uPA, MMP9, VEGF, VEGF-C)." (PMID 29774091, 2018).
adrenocortical cancer (3 papers, 2021 to 2023). "Here, we showed that RGZ dose-dependently inhibited the in vitro proliferation of the adrenocortical carcinoma primary tumor cell line, H295R, as well as of the metastatic cell line, MUC-1." (PMID 34834449, 2021). "Thus, we evaluated if this interaction may also exert any effect on CAIII and CAIX expression in both cell compartments, by assessing the reciprocal modulation of the two CAs in an in vitro coculture system set up between ASCs and the two adrenocortical cancer cell lines, H295R and MUC-1 cells." (PMID 36646964, 2023).
Allergy (3 papers, 2020 to 2022). An allergy is an immune response or reaction to substances that are usually not harmful. "Most pleiotropic associations were exhibited by rs479844 (AP5B1, OVOL1 genes), which was associated with dermatological and allergic diseases, and rs4072037 (MUC1 gene), which was associated with magnesium levels and gastroenterological cancer." (PMID 32637184, 2020). "This protein group includes proteins involved in cell stress response (HSPB1), mucosal protection and allergy (MUC1), complement activation (CD55) and actin polymerization (CAPG, APRT, TPPP3)." (PMID 35590254, 2022). "In this section, we focus on vaccines based on mannan carrier-antigen complex/conjugations, including mannan-mucin 1 (MUC1) fusion protein conjugation for tumor therapy, mannan-DNA vaccine and mannan-allergy vaccines." (PMID 32351942, 2020).
anaplastic large cell lymphoma (3 papers, 2014 to 2021). Anaplastic large cell lymphoma (ALCL) is a rare and aggressive peripheral T-cell non-Hodgkin lymphoma, belonging to the group of CD30-positive lymphoproliferative disorders, which affects lymph nodes and extranodal sites. "Monoclonal anti-MUC1 antibody is mouse IgG1 isotype derived from the GP1.4 hybridoma, reacts with the repetitive protein epitope and recognizes highly glycosylated episialin (MUC1) in tumors of epithelial cell origin and large cell anaplastic lymphoma." (PMID 24639126, 2014).
atrophic gastritis (3 papers, 2013 to 2025). "Moreover, MUC1 suppresses the IL-1β secretion by macrophages in response to H. pylori and thus protects against the development of atrophic gastritis, a step on the path to GC." (PMID 41154387, 2025).
autosomal dominant tubulo-interstitial kidney disease (3 papers, 2022 to 2025). "If autosomal dominant tubulo-interstitial kidney disease (ADTKD) due to a MUC1 variant is suspected, please seek kidney genetic expert advice before proceeding with testing." (PMID 40979400, 2025). "A variable number of tandem repeat (VNTR) region of MUC1 is associated with the formation of a frameshift, which results in a truncated protein responsible for a rare form of CKD, autosomal dominant tubulo-interstitial kidney disease (ADTKD)." (PMID 37365616, 2023).
benign breast disease (3 papers, 2009 to 2017). "MUC1 IP was performed in nine serum samples from patients with malignant and benign breast diseases as well as normal females with CASA values above the cut-off level (2 Units/ml)." (PMID 19715603, 2009).
cervical squamous cell carcinoma (3 papers, 2015 to 2024). A squamous cell carcinoma arising from the cervical epithelium. "In the future, we will further explore the molecular mechanism by which MUC1 regulates ERK phosphorylation in cervical squamous cell carcinoma." (PMID 38702644, 2024). "Taken together, these results indicated that the inhibitory effect of MK-8353 depended on the expression of MUC1 in cervical squamous cell carcinoma." (PMID 38702644, 2024). "And we will extend a cohort with large number of cases to evaluate the value of MUC1 in predicting the occurrence of cervical squamous cell carcinoma in future studies." (PMID 38702644, 2024). "Herein, we investigated the mechanism of MUC1 and identified a novel regulatory pathway in cervical squamous cell carcinoma." (PMID 38702644, 2024). "Then, we revealed the potential role and regulatory mechanism of MUC1 in cervical squamous cell carcinoma." (PMID 38702644, 2024). "In this study, we explored the expression of MUC1 in cervical squamous cell carcinoma." (PMID 38702644, 2024). "Next, we explored the regulatory mechanism of MUC1 in cervical squamous cell carcinoma." (PMID 38702644, 2024). "However, the expression of MUC1 in precancerous lesions of cervical squamous cell carcinoma remains unclear." (PMID 38702644, 2024). "MUC1 regulates ERK phosphorylation, and subsequently upregulates ITGA2 and ITGA3 expression to promote tumorigenesis in cervical squamous cell carcinoma." (PMID 38702644, 2024). "It has been reported that the MUC family genes, MUC1, MUC16 and MUC4, are upregulated in cervical squamous cell carcinoma." (PMID 25789025, 2015). "Overall, we discovered a novel regulatory pathway, MUC1/ERK/ITGA2/3, in cervical squamous cell carcinoma that may serve as a potential biomarker and therapeutic target in the future." (PMID 38702644, 2024). "Overall, we identified a novel pathway, MUC1/ERK/ITGAs, in cervical squamous cell carcinoma." (PMID 38702644, 2024).
chronic gastritis (3 papers, 2009 to 2022). Inflammation of the stomach that is chronic in nature. "In human patients with chronic gastritis, depletion of the MUC1 extracellular domain α-subunit, but not the transmembrane β-subunit, has been reported." (PMID 19816567, 2009).
ductal carcinoma (3 papers, 2020 to 2024). "We used T47D, a ductal carcinoma cell line, as MUC1 and TnMUC1 positive control." (PMID 38819641, 2024). "In case 3, MUC1 was expressed in the cell lumen, and the expression around the cell membrane was strongly positive, which was significantly higher than that in the surrounding ductal carcinoma." (PMID 37337182, 2023).